INS (insulin)
Diseases named in the same sentence as INS in open-access papers (continued):
Sharing a sentence is not in itself a finding about the gene and the disease.
Insulin resistance (continued). "Collectively, triterpenoids from C. paliurus could be developed as insulin sensitizers, which might have therapeutic potential for insulin resistance and hyperglycemia." (PMID 30621331, 2019). "Insulin resistance was evaluated by recording changes in fasting serum insulin or HOMA-IR." (PMID 31246234, 2019). "A similar pattern is observed for skeletal muscle with GC–A expression, which is inversely related to fat content, body mass index, fasting plasma insulin levels and insulin resistance, whereas NPR–C is upregulated in obese individuals with impaired glucose tolerance and type 2 diabetes." (PMID 31269783, 2019). "Thus, the individuals exhibiting the higher responses to both insulin and methylamine were probably those with the lower insulin resistance and thereby with the lower HOMA index." (PMID 31409018, 2019). "Of note, recent in vitro data using preadipocytes revealed that the tripeptides IPP (Ile-Pro-Pro) and VPP (Val-Pro-Pro), which are derived from milk casein, enhance insulin sensitivity and contribute toward the prevention of insulin resistance in the presence of tumor necrosis factor." (PMID 31340611, 2019). "Higher concentrations of S1P appear to impede insulin signaling leading to insulin resistance." (PMID 31067249, 2019). "Of all the potential pathological mechanisms of MetS, emerging evidence suggests that impaired insulin signaling and increased insulin resistance, as well as elevated status of chronic inflammation, are major risk factors that may induce skin diseases." (PMID 31824416, 2019). "Omentin V109D and FTO rs9939609 genetic variations may change insulin metabolism and have key roles in developing T2D through insulin resistance." (PMID 31200723, 2019). "An alternative hypothesis exists whereby primary insulin hypersecretion initiates insulin resistance." (PMID 31489455, 2019). "Furthermore, SIRT3 KO mice exhibited increased insulin resistance, which is underpinned by defective insulin-induced glucose uptake in skeletal muscle." (PMID 31130874, 2019). "The effectiveness of the measured plasma insulin signal may be further damped by the presence of insulin resistance, a condition where the responsiveness of tissues to plasma insulin is reduced." (PMID 31581241, 2019). "Insulin resistance (IR) is defined as a blunted response of insulin–tissue targets to insulin." (PMID 31121834, 2019). "Future studies on insulin-resistant adult cohorts that will specifically measure Hsp90β levels instead of circulating Hsp90 will further answer these questions and clarify the role of Hsp90β involvement in insulin resistance." (PMID 31885746, 2019). "T2D is characterized by increased blood glucose levels due to impairments in insulin release from pancreatic β-cells and insulin resistance, which is defined as decreased action of insulin on insulin-sensitive tissues like skeletal muscle (SKM), adipose tissue, and liver." (PMID 31622341, 2019). "Therefore, we aimed to conduct a systematic review and meta-analysis to evaluate the correlation between NC and glycemic parameters including FBG, serum fasting insulin, homeostasis model assessment-estimated insulin resistance (HOMA-IR) and HbA1c." (PMID 31289463, 2019). "Because resistance to insulin action on various organs and pathways characterizes type 2 diabetes, and together with inadequate compensatory insulin secretion drives its pathogenesis, many studies have sought mechanistic explanations for insulin resistance." (PMID 30357355, 2019). "TNF-α is a mediator of insulin resistance through its ability to block the action of insulin." (PMID 31736870, 2019). "In GDM patients, the insulin secretion is decreased by promoted insulin resistance rate." (PMID 31558153, 2019). "However, post-insulin treatment there was a gradual decrease of phospho-AKT/Total AKT signal from 1 h (50% reduction) to 4 h (80% reduction) signifying progressive insulin resistance." (PMID 31427921, 2019).
Insulin resistance (continued). "Prevailing theory has been that the elevations of circulating IGF-1 and insulin levels in insulin resistance and type 2 diabetes are both partly responsible for the acceleration of VSMC proliferation and restenosis causing stent failure in the treatment for coronary artery disease." (PMID 31562314, 2019). "Collectively, these data lend support to a possible role of CNTF as an insulin-sensitizer, which could be harnessed to overcome obesity-related adipose inflammation and insulin resistance." (PMID 31781039, 2019). "Firstly, TEF is related to serum insulin and insulin resistance." (PMID 31137899, 2019). "Insulin affects the metabolic function of many organs including muscle tissue, adipose tissue, and the intestine, with a consequent multitude of metabolic disturbances arising with the development of insulin resistance." (PMID 31920976, 2019). "The increase in FFA may cause dyslipidemia on the one hand, and on the other hand it may inhibit the use of glucose, reduce the sensitivity of insulin, and promote insulin resistance." (PMID 30902099, 2019). "Glucose, insulin, and glycated hemoglobin (HbA1c) levels were measured, the insulin resistance index (HOMA2-IR) was calculated, and the glycemic status (normoglycemic [n = 534]/impaired fasting glucose [IFG] [n = 252]/type 2 diabetes [T2D] [n = 24]) determined." (PMID 31222113, 2019). "However, fasted plasma insulin levels of HFD CD40fl/flCD11ccre mice had increased 1.7-fold compared to WT mice (unpaired t-test, p = 0.0476), indicating compensation of dysfunctional insulin signaling and worsened insulin resistance in CD40fl/flCD11ccre mice." (PMID 31604965, 2019). "In patients with newly diagnosed T2DM, glucotoxicity and lipotoxicity could be effectively reduced by early insulin therapy to alleviate insulin resistance and protect islet function." (PMID 31038562, 2019). "An acute impairment in the biological response to insulin in the brain, known as central insulin resistance, was identified during stroke and traumatic brain injury, for which excitotoxicity, which is caused by excessive glutamate release, is a key pathogenic factor." (PMID 31856878, 2019). "However, an increment in serum triglycerides, total cholesterol, fasting glucose, insulin, and Homeostasis Model Assessment-Insulin Resistance (HOMA-IR) was found in olanzapine medicated rats." (PMID 30717287, 2019). "Consequently, the insulin secretion/insulin resistance (disposition) index of beta cell function during the 0–30 min and 0–120 min time periods increased significantly (both p < 0.02)." (PMID 31470605, 2019). "The present trial aims at confirming whether insulin resistance, assessed with the homeostasis model assessment of insulin resistance (HOMA-IR) and the quantitative insulin sensitivity check index (QUICKI), is a risk factor for cutaneous melanoma." (PMID 31749765, 2019). "The increase in insulin concentration in the control group within the first three weeks might be compensatory for insulin resistance." (PMID 31484373, 2019). "The mechanisms of the anorexic effects of insulin include regulating food reward through DA signaling, and thus, impaired insulin sensitivity (i.e. insulin resistance) is expected to dysregulate DA signaling as occurs in rodent models of diet induced obesity (DIO)." (PMID 30849082, 2019). "Therefore, studies on the complex network of liver insulin signaling pathway can help us to understand the molecular mechanism of hepatic insulin resistance and type 2 diabetes and provide new solutions for the treatment of metabolic diseases." (PMID 30949394, 2019). "Moreover, DYRK1A up-regulation of IRS-1 ameliorates insulin resistance induced by chronic high insulin exposure in SH-SY5Y cells and rat primary neurons." (PMID 31723029, 2019).
Insulin resistance (continued). "At the end of the study, patients treated with plant extracts displayed a significant reduction of serum glucose (p < 0.001), insulin levels (p < 0.01), homeostatic model assessment for insulin resistance (HOMA-IR) index (p < 0.001), and CAP value (p < 0.01) compared to placebo." (PMID 31888241, 2019). "In addition, the LC/HP diet decreased homeostasis model assessment of insulin resistance (HOMA-IR) levels from 3.8 (insulin resistant) to 2.4 (insulin sensitive)." (PMID 31362773, 2019). "The GK rats showed moderate elevation in plasma glucose level (control, 4.92 ± 0.51 mM vs. diabetic 7.87 ± 0.85 mM), impaired glucose tolerance and decreased insulin sensitivity; determined by the so called homeostasis model assessment of insulin resistance (HOMA-IR)." (PMID 30720765, 2019). "Insulin resistance (or its inverse, insulin sensitivity) shows high inter-individual variability." (PMID 31208038, 2019). "Results obtained in in vitro and in vivo studies suggested that flavonoids improve insulin-sensitivity and therefore may exert a beneficial effect on insulin-resistance." (PMID 31027340, 2019). "Interestingly, C16- to C24-ceramide species have been shown to be the most associated with hyperinsulinemia and a strong HOMA-IR (homeostasis model assessment of insulin resistance, a test to measure the β-cell function and insulin sensitivity)." (PMID 30678043, 2019). "On average, NAFLD children were older; had higher waist circumference (WC), systolic BP, alanine aminotransferase (ALT), insulin, and homeostasis model assessment of insulin resistance (HOMA-IR); and lower concentrations of high-density lipoprotein cholesterol (HDL-C) (p < 0.05)." (PMID 31505904, 2019). "Insulin resistance is defined as a smaller than normal response to a constant amount of insulin." (PMID 31731774, 2019). "Hyperglycemia may develop either as a consequence of impaired insulin secretion or decreased insulin sensitivity (insulin resistance)." (PMID 31344877, 2019). "Adiponectin has strong anti-inflammatory and insulin-sensitizing functions and their plasma levels have been clearly demonstrated to be decreased as the body mass index (BMI) increases being oppositely correlated with insulin resistance." (PMID 31484347, 2019). "Obesity might increase the expression of some inflammatory cytokines and activate several inflammation-related signaling pathways, both of which are involved in the pathogenesis of insulin resistance by inhibiting insulin signaling and action." (PMID 31866871, 2019). "It is suggested that impaired insulin signaling leading to insulin resistance could have an effect on muscle metabolism (MPS and MPB) and endothelial dysfunction beyond glucose intolerance." (PMID 31828076, 2019). "Purified betanin regulated glucose levels, insulin, and insulin resistance." (PMID 31443409, 2019). "Thefasting blood glucose and insulin levels, as well as serum 25-hydroxyvitaminD and homeostasis model assessment of insulin resistance (HOMA-IR) levelswere measured at baseline and two months post treatment with a single doseof 300,000IU intramuscular vitamin D3." (PMID 31091067, 2019). "They uniquely speculated that obese women tend to have insulin resistance and higher levels of insulin in comparison to lean women and that potential ability of alcohol to improve those conditions may have led to a reduced endometrial cancer risk." (PMID 31284691, 2019). "Since skeletal muscle is the primary target for insulin-mediated glucose uptake, age-related changes in the structure and metabolism of this tissue are also thought to play a major role in the pathogenesis of insulin resistance in older adults." (PMID 31684154, 2019). "The preliminary evidence linking mitochondrial dysfunction to insulin resistance comes from studies performed in obese and insulin-resistant individuals who exhibited a decrease in skeletal muscle mitochondria oxidative capacity and defective lipid metabolism compared to healthy, lean controls." (PMID 31130874, 2019).
Insulin resistance (continued). "Thus, deletion of β cell GPR54 induces glucose intolerance in pregnancy by reducing glucose-induced insulin secretion, consistent with placental kisspeptin acting to compensate for pregnancy-induced insulin resistance by enhancing β cell function." (PMID 31619585, 2019). "Moreover, homeostatic model assessment-insulin resistance (HOMA-IR) was decreased from 2.1 to 1.4 while quantitative insulin sensitivity check index (QUICKI) was increased from 0.35 to 0.42." (PMID 31885810, 2019). "Glucose tolerance, insulin resistance and glucose-stimulated insulin secretion were evaluated." (PMID 31455371, 2019). "Chronically elevated levels of inflammatory cytokines could directly enhance insulin resistance and lead to disrupted insulin sensitivity, in turn impairing glucose and lipid metabolism." (PMID 30857216, 2019). "The antidiabetic effects of the seeds are attributed to galactomannan which decreases insulin resistance and glucose resorption from the gastrointestinal tract; 4-hydroxyisoleucin (4-OH-Ile) which increases insulin secretion, diosgenin and trigonelline due improving β-cell regeneration." (PMID 31658729, 2019). "We hypothesized that insulin, which is elevated in obesity-driven insulin resistance, would increase tumor glucose oxidation in obesity-associated tumors." (PMID 31188872, 2019). "Although the relative contribution of insulin secretion versus insulin action impairments in type 2 diabetes (T2D) depends on many factors, it has been extensively reported that obesity-related insulin resistance plays an important role in the onset and development of T2D." (PMID 31208038, 2019). "There are molecular mechanismsthat can elucidate insulin resistance in PCOS patients.It seems that a major contributor to insulin resistancein PCOS patients is a reduction in insulin sensitivitysecondary to a defect in insulin signaling." (PMID 30507086, 2019). "Due to its negative association with insulin resistance, adiponectin has been considered an insulin-sensitizing adipokine and is inversely related to adiposity." (PMID 31877943, 2019). "We have shown that increasing dietary protein from 15% to 30% of total food intake quantitatively increased insulin sensitivity from 4.6 (borderline insulin resistance) to 11.6 (insulin sensitive) in men with SCI who followed an 8-week low-carbohydrate/high-protein (LC/HP) dietary intervention." (PMID 31362773, 2019). "The progressive hyperinsulinaemia across quartiles could be due to primary insulin hypersecretion, compensation for insulin resistance or a combination of both." (PMID 31489455, 2019). "Consequently, the conditions for insulin resistance can be modeled by treating cells with insulin or TNF-α." (PMID 31635166, 2019). "Thus, insulin failure to activate the insulin pathway in the medial septum of 3×Tg-AD mice suggests that these mice developed a condition reminiscent of brain insulin resistance." (PMID 29736736, 2019). "Hyperglycemia occurs due to insufficient insulin levels and increased insulin resistance." (PMID 31574903, 2019). "Insulin resistance is a definition for insufficient response of tissues to the effect of insulin, resulting decreased insulin-mediated glucose uptake into the skeletal muscle, increased hepatic glucose production in the liver, and impaired suppression of lipolysis in adipose tissue." (PMID 31814873, 2019). "IRS-1 is the key molecule in insulin signaling and insulin resistance." (PMID 31723029, 2019). "Herein, we investigated the effect of EWH and egg white-derived peptide, IRW, on TNF-α-induced insulin resistance and its underlying molecular mechanism by testing glucose uptake, GLUT4 translocation, and insulin-signaling pathway using rat skeletal muscle cells (L6)." (PMID 29955954, 2019). "Higher glucose and insulin levels, and HOMA-IR predict the increasing risk of insulin resistance." (PMID 31847151, 2019).
Insulin resistance (continued). "Insulin resistance is a reduction in the response to insulin of specific tissues and results in reduced inhibition of lipolysis in adipose tissue, which, in turn, contributes to a reduced skeletal muscle glucose uptake and an increased hepatic glucose production." (PMID 30637483, 2019). "In addition, a recent study reported that CB1R activation in adipose tissue alters antilipolytic activity of insulin, a fact contributing to ectopic fat deposition involved in insulin resistance." (PMID 30800481, 2019). "Furthermore, it was shown that the induction of ER stress resulted in insulin resistance by weakening insulin transduction signal and preventing the phosphorylation of PKB." (PMID 30987118, 2019). "In obesity, altered insulin action and the consequental PI3K/Akt signaling pathway alteration in skeletal muscle, liver and adipose tissue may cause systemic insulin resistance." (PMID 31130916, 2019). "Moreover, these patients had significantly higher fasting glucagon levels even in the face of elevated fasting plasma insulin, suggesting impaired cross-talk between α and β-cells due to insulin resistance." (PMID 30948746, 2019). "Since patients that use insulin probably have a higher degree of insulin resistance these findings suggest that NE concentrations in plasma could associate with the levels of insulin resistance." (PMID 31046673, 2019). "Adipose tissue insulin resistance was calculated as the product of insulin and FFA concentrations." (PMID 30637483, 2019). "Previous studies examining the relationship between iron and adipose tissue function reveal that excess iron promotes adipose insulin resistance by directly interfering with insulin-insulin receptor binding and promoting the expression of genes that inhibit insulin receptor/ effector function." (PMID 30820238, 2019). "Insulin and high glucose in obese and insulin resistance conditions might induce the heparanase upregulation." (PMID 31890010, 2019). "It is noteworthy, that EVOO-based HFD significantly decreased fasting glycemia, insulinemia and insulin resistance at the end of the interventional study, as well as significantly lowered insulin release after a glucose challenge and significantly improved KITT." (PMID 31383924, 2019). "We demonstrated that urinary CML levels were associated with markers of insulin resistance such as fasting and 2 h insulin levels and HOMA-IR, but not with cardiovascular parameters, after adjustment for age and BMI or WHR." (PMID 31295874, 2019). "The most recent evidence from an MR study suggests the red blood cell trait, reticulocyte count, may be a causal factor for IHD25, so we similarly examined the role of insulin and insulin resistance in reticulocyte count." (PMID 31508506, 2019). "Furthermore, UBC-SKO mice were glucose intolerant and had significantly higher concentrations of serum glucose as well as insulin 12 weeks after tamoxifen treatment, consistent with insulin resistance." (PMID 31404087, 2019). "Of note, in vivo ALS-T2DM-IgGs may target peripheral insulin-sensitive tissues of patients, leading to insulin resistance." (PMID 31826954, 2019). "Second, some ART characteristics may be in charge of insulin resistance and the need for insulin therapy, such as PCOS, the number of embryo transfer, and administration of GnRH agonist during the COS cycle in ART." (PMID 31656196, 2019). "Knowledge of this interplay could further aid our understanding of how FFAR1 affects insulin sensitivity, insulin resistance, and overall β-cell function in T2D." (PMID 31426858, 2019). "Additionally, different studies have proposed potential DNA methylation biomarkers in relation to plasma insulin levels, insulin secretion and insulin resistance such as those located in PPARGC1A, HTR2A, LY86, TFAM, GIPR, ADIPOQ, and IGFBP3 genes." (PMID 31208038, 2019).